FGFR3 (fibroblast growth factor receptor 3)
Diseases named in the same sentence as FGFR3 in open-access papers (continued):
Sharing a sentence is not in itself a finding about the gene and the disease.
bladder cancer (continued). "However, we also noted some studies which claimed that FGFR3 demonstrated tumor suppressor properties in pancreatic cells with epithelial phenotype and predicted favorable prognosis in bladder cancer when overexpressed." (PMID 27829236, 2016). "Oncogenic FGF receptor 3 (FGFR3)-BAIAP2L1 fusion gene was identified in bladder cancers and lung cancers, and its identification may aid in selecting patients for FGFR-targeted therapy." (PMID 26222696, 2015). "In the present study, it was identified that miR-99a may function as a tumor suppressor through repression of FGFR3 in bladder cancer." (PMID 24944696, 2014). "The overexpression of FGFR3 has also been observed in a number of tumor panels in bladder cancer." (PMID 24944696, 2014). "Additionally, this study provided the first evidence that miRNA-99a is likely to directly target fibroblast growth factor receptor 3 in bladder cancer." (PMID 24944696, 2014). "Interestingly, TACC3 has been identified as a fusion partner to FGFR3 in bladder cancer, squamous cell lung cancer, oral cancer, head and neck cancer and glioblastoma multiforme." (PMID 24550739, 2014). "Therefore, FGFR3 deserves close scrutiny as a potential target for the inhibition in bladder cancer." (PMID 24944696, 2014). "Western blot analysis was performed to analyze whether FGFR3 was decreased following transfection of the miR-99a mimics in the bladder cancer cell lines, T24 and EJ." (PMID 24944696, 2014). "In bladder cancer, FGFR3 mRNA expression is hypothetically up-regulated by miR-100 down-regulation." (PMID 23717626, 2013). "Interestingly, these pathways are downstream of the EGFR and ErbB2 family proteins whose expression and activity are related to bladder cancer progression, as well as ErbB3, FGFR3 and HRAS that are active in superficial tumors." (PMID 23383328, 2013). "Interestingly, several bladder cancer risk variants including MYC and FGFR3/TACC3 show stronger association with low risk tumors, confirming the heterogeneous nature of bladder cancer." (PMID 23752272, 2013). "Based on clinical and molecular evidence, two progression pathways have been described in bladder cancer, the Ta pathway presenting high frequency of FGFR3 mutation and the Cis pathway with no or low rate of FGFR3 mutation." (PMID 22724020, 2012). "This case study demonstrates that the FGFR3 assay is a beneficial addition to the methodologies used in real-life clinical settings for diagnosing not only bladder cancer but also for diagnosing the less common and more difficult to detect upper urinary tract urothelial carcinoma." (PMID 22873290, 2012). "FGFR3 amplification and/or overexpression was reported in rhabdomyosarcoma and bladder cancer." (PMID 22551002, 2012). "However several reports have examined FGFR3 protein expression in bladder carcinomas, describing an increase in a high proportion of tumours, particularly in the low-grade and low-stage subgroups." (PMID 22899908, 2012). "RAS mutations, which are observed in about 10% of bladder cancers and are never found with FGFR3 mutations, are thought to affect the FGFR3 signaling pathway." (PMID 23272046, 2012). "Two main progression pathways have been so far identified in bladder cancer, the Ta pathway characterized by a high frequency of FGFR3 mutation and the carcinoma in situ (Cis) pathway where no or infrequent FGFR3 mutations have been identified." (PMID 22724020, 2012).
bladder cancer (continued). "Therefore, although the expression of FGFR1 was higher than that of FGFR3 in the present study, the authors reaffirmed the important role of FGFR3 in the development and progression of bladder cancer, and our results are consistent with those of previous reports." (PMID 41228379, 2025). "In bladder cancer, FGFR3 mutations predominantly occur in low-grade, non-muscle-invasive subtypes with papillary growth patterns and well-differentiated histology, suggesting they may define a distinct molecular subtype." (PMID 41514604, 2025). "Additionally, it was indicated that FGFR1 could play a crucial role in invasion and metastasis, but its role in driving bladder cancer cell proliferation might be less important than FGFR3." (PMID 39031286, 2024). "In addition, FGFR3 mutations in UTUC may be differentiated according to the disease stage, similar to bladder cancer." (PMID 38592174, 2024). "However, they still agree that FGFR3 overexpression is associated with lower pT stage and lower grade, and may be associated with favorable features, even though these subclones exhibit wild-type FGFR3 in bladder cancer." (PMID 35563543, 2022). "However, whether these mechanisms extend to other FGFR3-fusion driven bladder cancer cell lines is unknown." (PMID 35501832, 2022). "Thus, FGFR3 steers the biosynthesis of monounsaturated fatty acids in bladder cancer, suggesting that FGFR3 may potentially also regulate lipid homeostasis in MM." (PMID 33494394, 2021). "Notably, we did not detect any activating mutations in FGFR3 in our cohort, which have been shown to predict responses to tyrosine kinase inhibitors in bladder cancer." (PMID 34464379, 2021). "Furthermore, anti-FGFR3 therapy slows bladder cancer growth, especially in FGFR3-mutant tumors." (PMID 33243261, 2020). "However, although mutation of HRAS as well as FGFR3 and PI3K/AKT/mTOR components are associated with development of noninvasive bladder cancer, it is unknown if the hyperplastic and/or transformed state depends upon maintenance of oncogene expression." (PMID 30670749, 2019). "To better understand the role of FGFR3 in invasive bladder cancer, we examined the process of tumour development induced by the tobacco carcinogen OH‐BBN in genetically engineered models that express mutationally activated FGFR3 S249C or FGFR3 K644E in the urothelium." (PMID 30043421, 2018). "Therefore, FGFR3 may promote the development of bladder cancer by regulating cell division, response to type I interferon signaling, and blood vessel morphogenesis." (PMID 28320388, 2017). "Thus, we screened the bladder cancer recurrence-related genes from the FGFR3-centered PPI network." (PMID 28320388, 2017). "Pre-clinical data suggest that FGFR3 mutations are exclusive to non-inflamed bladder cancers (~ 30% of tumors), a subgroup characterized by absence of CD8 tumor infiltrating lymphocytes (CD8 TILs), worsen prognosis, and lower chance of responding to PD-L1 blockade." (PMID 27409839, 2016).
bladder cancer (continued). "In bladder cancers, a multiple regional epigenetic silencing phenotype was found to occur in a subset of aggressive tumors of the carcinoma in situ pathway but not in tumors driven by mutations in FGFR3." (PMID 26235388, 2015). "Since the low frequency of copy number variation in the Ta grade 1 and 1–2 samples might be explained by presence of normal tissue rather than bladder cancer in those specimens, we examined them for mutations in FGFR3." (PMID 23593348, 2013). "Finally, tentative proliferative or anti-proliferative mechanisms can be connected with established bladder cancer deregulations, namely Epidermal Growth Factor Receptor (EGFR) over-expression and Fibroblast Growth Factor Receptor 3 (FGFR3) activating mutations." (PMID 24250280, 2013). "Deregulated genes during bladder cancer pathogenesis in the FGFR3-non-mutated tumor pathway." (PMID 22724020, 2012). "Dual targeting of FGFR3 and ERBB3 showed to overcome resistance of FGFR3-fusion driven bladder cancer." (PMID 41409251, 2025). "In bladder cancer (BC), chromosomal translocations can fuse TACC3 to FGFR3, resulting in constitutive activation of FGFR3 kinase and driving cellular transformation." (PMID 40246827, 2025). "FGFR3 is an important therapeutic target in bladder cancer, and clinical studies have shown the benefit of FGFR inhibitors in a subset of bladder cancer patients." (PMID 39031286, 2024). "For example, FGFR3 expression was elevated in hypoxia and HIF-1α-dependent manners in bladder cancer." (PMID 38542288, 2024). "In bladder cancer, FGFR1 and FGFR3 alterations are commonly found and they have been implicated in the pathogenesis of UBC." (PMID 39031286, 2024). "For the early detection of bladder cancer biomarkers, a sensitive nucleic acid biosensor has been created, employing a silicon resonator as an optical sensor that targets FGFR3 (fibroblast growth factor receptor 3) and HRAS (Harvey RAS) in urine samples." (PMID 39685966, 2024). "ETV5 has been shown to be involved in the crosstalk between FGFR3 signaling and the Hippo pathway; upregulates the expression of genes involved in EMT; and mediates proliferation and anchorage independent growth of bladder cancer cells." (PMID 39031286, 2024). "Targeting FGFR3 and PD-L1 increased CD8+ T-cell-induced anticancer efficacy and exhibited effective tumor suppression in bladder cancer." (PMID 37215134, 2023). "Approximately 50% of bladder cancers harbor FGFR genetic alterations; 75% of the NMIBC and approximately 15% of high-grade invasive urothelial cancers harbor FGFR3 genetic alterations, and 2% of urothelial cancers carry FGFR2 mutations." (PMID 37681152, 2023). "In bladder cancer, activation of the SRC pathway by FGFR3 leads to resistance of tumor cells to FGFR inhibitors, such as infigratinib or erdafitinib." (PMID 37750089, 2023). "Two of these (FGFR3 and ERBB3) are known cancer drivers in CGC and already being targeted by drugs for bladder cancer." (PMID 35035776, 2022). "We established an expression profile of 22 immune cells in the bladder cancer samples using the CIBERSORT algorithm, so as to investigate the impact of FGFR3 on immune cell infiltration." (PMID 35991125, 2022). "The exact pathway of bladder cancer carcinogenesis in correlation with FGFR3 is not established, yet some data showed that FGFR3 mutations suppressed the inflammatory response in early stages and that further inflammation was corelated rather with progression than with FGFR3 mutation." (PMID 35326568, 2022).
bladder cancer (continued). "Taken together, FGFR3 expression, which is related to TME remodeling and tumor metastasis, is a relevant marker of tumor metastasis in bladder cancer." (PMID 35991125, 2022). "Utilizing comprehensive bioinformatic analysis, we found FGFR3 as a target for TME remodeling status and possibly as a predictor of clinical outcomes, including survival of bladder cancer patients, distant tumor metastasis, and immunotherapy response." (PMID 35991125, 2022). "Long term treatment of FGFR3-fusion harbouring SW780 and RT4 bladder cancer cell lines with the FGFR inhibitor BGJ398 resulted in the establishment of resistant clones." (PMID 35501832, 2022). "Therefore, this study is aimed at investigating whether FGFR3 is promising as a biomarker of TME remodeling to explain underlying mechanisms involved in tumorigenesis and metastasis, which may help to make decisions on treatments for bladder cancer." (PMID 35991125, 2022). "Importantly, this clinical trial was performed in patients having failed chemotherapy and/or immunotherapy, and thus these treatment outcomes may not be applicable to all bladder cancers with FGFR3 mutations." (PMID 34638374, 2021). "The most common FGFR3 fusions are with the transforming acidic coiled-coil containing protein 3 (TACC3) and have been discovered in glioblastoma, bladder cancer, and lung cancer." (PMID 34272467, 2021). "MPT0L145 is a PIK3C3/FGFR3 inhibitor which simultaneously promotes autophagosome formation via FGFR3 inhibition and impairs autophagy flux via PIK3C3 inhibition in bladder cancer cells with FGFR3 activation." (PMID 34885226, 2021). "Among the candidate molecules associated with urothelial differentiation are KRT20, a well established luminal marker, and FGFR3, STAG2, and PIK3CA—three major bladder cancer genes commonly altered in luminal tumors." (PMID 32635360, 2020). "The panel of cell lines included in our study possesses diverse molecular alterations in FGFR3, RAS, PIK3CA, PTEN, TSC1 and mTOR that are capable of influencing response to PI3K pathway inhibition and are very frequent in bladder cancer specimen." (PMID 29357370, 2018). "We have selected three bladder cancer cell lines (T24, 5637, and HT1376), representative of two distinct molecular pathways to invasive cancer (FGFR3/CCND1and E2F3/RB1), and widely explored by us in the establishment of novel therapeutic schemes." (PMID 27835695, 2016). "Three of the most studied bladder cancer cell lines (T24, 5637, and HT1376), reflecting different molecular pathways for cell invasion (FGFR3/CCND1and E2F3/RB1), were chosen envisaging the identification of a ubiquitous reference gene." (PMID 27835695, 2016). "FGFR3 and hsa-miR-100 pair in BLCA have been identified by this approach and both of them were reported as the bladder cancer gene and miRNA." (PMID 27766936, 2016). "Accordingly, three bladder cancer cell lines (T24, 5637, and HT1376) representative of two distinct carcinogenesis pathways to invasive cancer (FGFR3/CCND1 and E2F3/RB1) were used." (PMID 27835695, 2016).
bladder cancer (continued). "In addition, we recently examined a prevalent occupational exposure susceptibility variants associated with increased bladder cancer risk, and observed an additive interaction for rs798766 (TMEM129-TACC3-FGFR3) with the interaction more apparent in patients with tumors positive for FGFR3 expression." (PMID 27154171, 2016). "As an initial assessment of the functional consequence of TAK1 and FGFR3 signaling, we evaluated cell adhesion in the MGHU3 UC line, based on previous studies using T24 bladder cancer cells." (PMID 24466111, 2014). "In contrast to FGFR3 and FGFR1, FGFR2 appears to have a protective or tumour-suppressor role in bladder cancer." (PMID 22899908, 2012). "Overactive FGFR3 and ERBB2 in bladder cancer presumably would activate Stat3 that is down-stream to these two receptor tyrosine kinases." (PMID 18939995, 2008). "The mechanism of FGFR3 overexpression in bladder cancer is not completely clear, but dysregulation of FGFR3 expression due to various alterations including microRNAs (miRs) and transcription factors have been described." (PMID 39031286, 2024). "Although OncoKB indicates FDA approval for erdafitinib in FGFR3-mutated bladder cancer, there are currently no FDA-approved treatments tailored specifically to patients with FGFR3 oncogenic mutant pancreatic cancer." (PMID 38542259, 2024). "Moreover, aberrantly activated FGFR3 was reported to induce AKT pathway and GSK-3β inhibitory phosphorylation in bladder cancer cell lines, thus hampering c-Myc degradation." (PMID 39482742, 2024). "Indeed, c-Myc can directly induce FGFR2 and FGFR3 transcription in SNU-16 gastric cancer cell line and in bladder cancer cell lines, respectively." (PMID 39482742, 2024). "However, to date, for patients with advanced or metastatic bladder cancer and alterations in the FGFR2 or FGFR3 gene, targeted therapy based on the inhibitor of FGFR (erdafitinib) is available." (PMID 39768623, 2024). "FGFR3 fusions are most frequently observed in GBM, lung and bladder cancers." (PMID 39590169, 2024). "In addition, based on the FGFR3 fusions and overexpression of FRS2, we also included SW780 (urinary bladder carcinoma), RT-112 (urinary bladder carcinoma), M059K (glioblastoma) and SKOV3 (ovarian adenocarcinoma) cell lines." (PMID 36495366, 2023). "p-FGFR3 and NEDD4 co-localized at the cell surface of bladder cancer cells." (PMID 37497216, 2023). "While genes such as FGFR3 and PIK3CA may have a high frequency in the early stages of bladder cancer, and are still detectable, they are outcompeted by cells with driver mutations associated with MIBC." (PMID 37175559, 2023). "Interestingly, several of our potential targets are currently in clinical trials for the treatment of bladder cancer including EGFR, HDAC3, FGFR3, ERBB3." (PMID 35035776, 2022). "The tendency of mutual exclusivity between AHR, FGFR3, and PIK3CA alterations may indicate convergence on the same pathway, although a fully independent parallel oncogenic pathway in bladder cancer driven by AHR cannot be excluded." (PMID 35710704, 2022). "It is known that FGFR3 alterations lead to oncogenic signaling through the MAPK and PI3K pathways and that these alterations are particularly sensitive to FGFR inhibitors, leading to the approval of erdafitinib for patients with advanced bladder cancer." (PMID 36551663, 2022).